CXXC5 (CXXC finger protein 5)
Description:
May indirectly participate in activation of the NF-kappa-B and MAPK pathways. Acts as a mediator of BMP4-mediated modulation of canonical Wnt signaling activity in neural stem cells (By similarity). Involved in myelopoiesis. Transcription factor. Binds to the oxygen responsive element of COX4I2 and represses its transcription under hypoxia conditions (4% oxygen), as well as normoxia conditions (20% oxygen). May repress COX4I2 transactivation induced by CHCHD2 and RBPJ. Binds preferentially to DNA containing cytidine-phosphate-guanosine (CpG) dinucleotides over CpH (H=A, T, and C), hemimethylated-CpG and hemimethylated-hydroxymethyl-CpG.
Synonyms: CF5; RINF; HSPC195; WID
Tractability: PROTAC: ubiquitination databases record sites on it; its protein half-life has been measured.
Gene: Protein-coding gene on chromosome 5 (139,646,375 to 139,683,882, forward strand). Ensembl gene ENSG00000171604.
Subcellular location: Nucleus; Cytoplasm
Subcellular location (Human Protein Atlas): Nucleoplasm; Cytosol
Pathways (Reactome):
Signal Transduction: Estrogen-dependent gene expression
Gene Ontology:
Molecular function: DNA-binding transcription factor binding; methyl-CpG binding; sequence-specific DNA binding; zinc ion binding; DNA binding
Biological process: negative regulation of transcription by RNA polymerase II; positive regulation of canonical NF-kappaB signal transduction; regulation of generation of precursor metabolites and energy
Cellular component: nucleoplasm; cytoplasm; nucleus
Genetic constraint (gnomAD): Loss-of-function variants: 2 observed, 17.15 expected, observed/expected ratio (o/e) 0.12, 90% interval 0.047 to 0.37. The upper end of that interval is the gene's LOEUF score, 0.37, which puts it in group 1 of 6, group 1 being the genes least tolerant of losing a copy. Missense variants: 343 observed, 468.06 expected, observed/expected ratio (o/e) 0.73, 90% interval 0.67 to 0.8. Synonymous variants: 171 observed, 198.73 expected, observed/expected ratio (o/e) 0.86, 90% interval 0.76 to 0.98.
Homologues: Orthologues: chimpanzee CXXC5 (99% identical), macaque CXXC5 (98% identical), rat Cxxc5 (94% identical), pig CXXC5 (93% identical), mouse Cxxc5 (93% identical), dog CXXC5 (93% identical), rat Cxxc5l1 (92% identical), guinea pig CXXC5 (92% identical), zebrafish cxxc5a (51% identical), zebrafish cxxc5b (44% identical). Paralogues in human: CXXC4 (33% identical).
Diseases named in the same sentence as CXXC5 in open-access papers:
CXXC5 is named in the same sentence as 70 diseases in open-access papers, as found by Europe PMC text mining. Sharing a sentence is not in itself a finding about the gene and the disease. The quoted sentences say what the papers report.
breast cancer (14 papers, 2015 to 2025). A primary or metastatic malignant neoplasm involving the breast. "For another example, CXXC5 overexpression has been observed to be associated with a poor prognosis for estrogen receptor–positive (ER+) breast cancer." (PMID 36857450, 2023). "Growth curve measurements indicated that CXXC5, CUL4B, or MTA1 stable knockdown reduced the growth ability of breast cancer cells and that CXXC5, CUL4B, or MTA1 overexpression enhanced the growth of MCF-7 cells." (PMID 36539038, 2023). "Overall, these results indicate that CXXC5 expression is upregulated by vitamin B2 and downregulated by vitamin D treatment and contributes to immune escape of breast cancer cells." (PMID 36539038, 2023). "Next, we analyzed CXXC5 mRNA expression levels in breast carcinoma specimens with paired paracancerous tissues from 11 breast cancer patients using RT–qPCR." (PMID 36539038, 2023). "We detected a higher CXXC5 mRNA expression level in breast carcinomas than in adjacent tissues in seven of these paired samples." (PMID 36539038, 2023). "We, as others, find that high levels of CXXC5 expression predict poor overall survival, particularly in ERα-overexpressing luminal breast cancer patients." (PMID 32249801, 2020). "We found that the mean CXXC5 expression is significantly higher in breast cancer than that observed with normal breast tissue." (PMID 32249801, 2020). "CXXC5 was first found in myeloid leukemia, and later, CXXC5 overexpression was found in breast cancer, prostate cancer, and other malignant diseases." (PMID 32337277, 2020). "One projection would then be that a de-regulated CXXC5 expression contributes to the initiation and/or progression of breast cancer." (PMID 27886276, 2016). "Zinc finger protein CXXC5 promotes breast cancer by regulating TSC1/mTOR signaling pathway." (PMID 39717098, 2024). "Together, these data confirm that high expression of CXXC5 promotes breast cancer development." (PMID 36539038, 2023). "Moreover, The Cancer Genome Atlas analysis showed strikingly increased expression of CXXC5 in breast cancer samples." (PMID 36539038, 2023). "However, the role of CXXC5 depends on the specific type of cancer, as CXXC5 has been reported to function as an oncogene in solid tumors, such as breast cancer, malignant melanoma, and papillary thyroid cancer." (PMID 36539038, 2023). "We revealed that CXXC5 expression in breast cancer is upregulated by vitamin B2 stimulation and that the expression level of CXXC5 is negatively correlated with vitamin D treatment and positively correlated with the degree of malignancy and poor prognosis of breast carcinomas." (PMID 36539038, 2023). "We demonstrated that in breast cancer cells, CXXC5 is responsible for initiating the transcriptional repression of TSC1, followed by monoubiquitination of H2AK119 by the CRL4B complex and NuRD (MTA1) complex–mediated histone deacetylation, which create a repressive chromatin environment." (PMID 36539038, 2023). "Moreover, mRNA levels of CXXC5 positively correlate with both mRNA and protein levels of ERα in breast cancer patients." (PMID 32249801, 2020). "Since CXXC5 is an E2-ERα responsive gene, CXXC5 could indeed participate in the initiation and progression of breast cancer driven by a de-regulated E2-ERα signaling." (PMID 32249801, 2020). "In keeping with this prediction is the findings using expression analyses of breast tumor and breast tumor data sets that high levels of CXXC5 expression is associated with poor prognosis and is an unfavorable prognostic factor in breast cancer without or with ER antagonist treatment." (PMID 27886276, 2016). "The expression of CXXC5, CUL4B, and MTA1 increased during the occurrence and development of breast cancer, and correspondingly, TSC1 expression decreased." (PMID 36539038, 2023).
breast cancer (continued). "The TET2-interacting proteins IDAX/CXXC4 and RINF/CXXC5 are overexpressed in a number of solid tumours, including breast cancer and colorectal cancer, and have been reported to negatively affect TET2 stability and function." (PMID 37667220, 2023). "We detected significantly upregulated expression of CXXC5, CUL4B, or MTA1 in breast carcinoma samples compared with that in normal tissues, and their expression levels increased with the histological grades of the tumor specimens." (PMID 36539038, 2023). "Our ongoing studies aiming at the dissection of the role of CXXC5 in E2-ERα signaling could provide important insights into the mechanism of E2-mediated cellular events, and consequently the development of additional and/or alternative treatment modalities to combat breast cancer." (PMID 27886276, 2016). "For instance, CXXC5 is a retinoid-inducible gene, and it mediates the proliferative responses of IGFs and HER2 in breast cancer." (PMID 25888236, 2015). "Consistent with this, we found that the mean of CXXC5 expression is higher in ERα+ luminal breast tumors compared to that observed with normal-like and ERα-negative breast cancer subtypes, including HER2+ and Basal-like tumors." (PMID 32249801, 2020). "Importantly, higher levels of the mean CXXC5 expression predict a poor overall survival only in luminal patients while the expression levels of CXXC5 are not prognostic in HER2+ or Basal-like subtypes, further supporting its clinical relevance to ER+ breast cancer." (PMID 32249801, 2020).
acute myeloid leukemia (10 papers, 2013 to 2025). Acute myeloid leukemia (AML) is a group of neoplasms arising from precursor cells committed to the myeloid cell-line differentiation. "The CXXC5 gene encodes a transcriptional activator with a zinc-finger domain, and high expression in human acute myeloid leukemia (AML) cells is associated with adverse prognosis." (PMID 25605239, 2015). "Consistent with the functional importance of CXXC5 in physiology, de-regulated expressions of CXXC5 have been reported to correlate with the development of various pathologies including acute myeloid leukemia (AML), gastric, prostate, and breast cancer." (PMID 34341443, 2021). "In addition, CXXC5 also acts as a tumor suppressor gene in acute myeloid leukemia, as low CXXC5 expression is correlated with upregulation of cell cycling genes and Wnt signaling." (PMID 36539038, 2023). "The CXXC5 gene is evolutionarily conserved, with a length of 35.5 kbp, and localized on human chromosome 5q31.2, where it is close to regions frequently deleted in patients with acute myeloid leukemia (AML) or myelodysplastic syndrome (MDS) and found to be an abnormal fusion partner with MN1." (PMID 39806388, 2025). "Furthermore, we recently described that CXXC5 is expressed in primary acute myeloid leukemia (AML) cells; this expression shows a wide variation between patients and high levels are associated with an adverse prognosis and resistance to chemotherapy-induced apoptosis." (PMID 25605239, 2015). "We investigated CXXC5/RINF expression in primary human acute myeloid leukemia (AML) cells derived from 594 patients, and a wide variation in CXXC5/RINF mRNA levels was observed both in the immature leukemic myeloblasts and in immature acute lymphoblastic leukemia cells." (PMID 23988457, 2013).
hepatocellular carcinoma (6 papers, 2019 to 2025). A malignant tumor that arises from hepatocytes. "Recently, two independent investigations have implicated CXXC5 in the development of hepatocellular carcinoma (HCC), a pathology intimately associated with liver fibrosis." (PMID 34621736, 2021). "Moreover, evidence indicates that CXXC5 can facilitate the TGF-β signaling pathway in hepatocellular carcinoma (HCC) by interacting with HDAC1, and its overexpression was discovered to result in apoptosis and cell cycle arrest in HCC." (PMID 39806388, 2025). "Finally, a number of in vitro studies in hepatoma cells have revealed that TGF-β treatment may either dampen the expression of Id1 or induce the expression of CXXC5 transcription factors to promote TGF-β signaling and suppress cancer cell proliferation." (PMID 35205692, 2022). "For example, in hepatocellular carcinoma, downregulation of CFIm25 subunit of cleavage factor results in high expression of PSMB2 and CXXC5 by increasing the usage of the proximal polyadenylation site." (PMID 31039132, 2019). "In addition, we have previously reported that CXXC5 is a target gene and functional mediator of TGF‐β in hepatocellular carcinoma (HCC) cells, contributing to the tumour‐suppressive functions of TGF‐β by promoting cell cycle arrest and apoptosis." (PMID 30479059, 2019).
leukemia (5 papers, 2013 to 2024). A malignant (clonal) hematologic disorder, involving hematopoietic stem cells and characterized by the presence of primitive or atypical myeloid or lymphoid cells in the bone marrow and the blood. "Despite CXXC5 being deleted in leukemia, it is overexpressed in solid tumors, which is consistent with our finding demonstrating the oncogenic potential of CXXC5." (PMID 36539038, 2023).
Obesity (5 papers, 2019 to 2022). Accumulation of substantial excess body fat. "The pathological significance of the CXXC5 function was indicated by suppression of Wnt/β-catenin signaling with overexpression of CXXC5 in the adipocyte tissues of patients with obesity as well as the early adipogenic differentiation of preadipocytes." (PMID 36450849, 2022). "In conclusion, activation of the Wnt/β-catenin signaling by inhibiting the interaction of CXXC5 and Dvl by small molecule-mediated interference is a potential therapeutic approach for treating obesity and insulin resistance." (PMID 36450849, 2022). "The systemic effectiveness of KY19334 on the anti-obesity was acquired by blockade of the function of the aberrantly overexpressed CXXC5 and subsequent inhibition of the Wnt/β-catenin signaling suppression in the early developmental stage of obesity by HFD." (PMID 36450849, 2022). "The role of CXXC5 in obesity was correlated with high induction of the inflammation markers and cytosolic accumulation of CXXC5 was inversely correlated with β-catenin in the metabolic tissues of the HFD-induced obese mice." (PMID 36450849, 2022). "The small molecule approach interfering CXXC5 function provides a potential treatment of overall metabolic abnormalities as well as obesity involving over nutrition related to the HFD." (PMID 36450849, 2022). "Overall, CXXC5 overexpression plays a role as a major driver in the adipogenic differentiation the obesity." (PMID 36450849, 2022). "Taken together, our findings revealed that the small molecular approach for activating Wnt/β-catenin signaling via interference of the CXXC5-Dvl protein–protein interaction (PPI) provides a potential anti-obesity approach against over-nutrition involving HFD." (PMID 36450849, 2022). "An approach for restoring the suppressed Wnt/β-catenin signaling via blockade of CXXC5-Dvl PPI offer a novel approach for anti-obesity with the improvement of metabolic parameters on HFD-mediated over nutrition." (PMID 36450849, 2022). "Here, we show that CXXC5 is overexpressed with suppression of Wnt/β‐catenin signalling in visceral adipose tissues of patients with obesity‐related diabetes." (PMID 35384342, 2022). "This involvement is corroborated by genetic studies of body mass index in humans, describing a role played in obesity by the CXXC5 gene in Americans and the PSD2 gene in the Japanese population." (PMID 31199810, 2019). "Indirect activation of Wnt/β-catenin signaling, actually its restorative activation by the interference of the CXXC5 function, could be an effective and safe approach for anti-obesity." (PMID 36450849, 2022). "By illustrating the role of Cxxc5 in inhibiting the Wnt/β-catenin pathway related to adipogenic differentiation and a small molecule-mediated interference of the Cxxc5 function up-regulating Wnt/β-catenin signaling is suggested as a new potential anti-obesity target." (PMID 36450849, 2022). "The Cxxc5−/− mice resisted obesity and obesity‐related insulin resistance when fed an HFD." (PMID 35384342, 2022). "Thus we reasoned that CXXC5 might be highly expressed with suppression of Wnt/β-catenin signaling in the early adipogenic differentiation during the development of obesity." (PMID 36450849, 2022). "Additionally, we suggest CXXC5 as a new biomarker for metabolic diseases, and its overexpression may be a major driver in the pathogenesis of multiple obesity‐related metabolic diseases." (PMID 35384342, 2022). "In contrast, the mRNA levels of CXXC5 and DKK‐1, which are negative regulators of the Wnt/β‐catenin signalling, were high in the visceral adipose tissues of patients with obesity‐related T2DM." (PMID 35384342, 2022). "As for the HFD‐fed Cxxc5−/− mice, HFD‐fed Cxxc5+/+ mice administered KY19334 revealed a reduction in abnormal metabolic phenotypes, such as obesity, insulin resistance and other diabetes‐related phenotypes." (PMID 35384342, 2022).
Obesity (continued). "HFD‐induced obesity did not occur in Cxxc5−/− mice, and their body weights were similar to those of Cxxc5+/+ mice fed NCD without alterations in food intake." (PMID 35384342, 2022). "Consistent with reduced obesity, HFD‐fed Cxxc5−/− mice exhibited markedly improved glucose tolerance and insulin sensitivity, with improved levels of metabolic parameters, including leptin, resistin, adiponectin, TGs, total cholesterol and HDL‐cholesterol levels." (PMID 35384342, 2022). "To elucidate the clinical implications of the role of CXXC5 in NASH development, we investigated the mRNA expression profiles of CXXC5 and Wnt-responsive genes in NASH patients with obesity using gene set enrichment analysis (Gene Expression Omnibus (GEO): GSE48452)." (PMID 36114279, 2022). "The anti-obesity effects of KY19334 could be acquired by suppression of early adipogenic differentiation, the initial event of obesity, accomplished by controlling the function of CXXC5 by the interference of the Cxxc5-Dvl PPI." (PMID 36450849, 2022).
breast adenocarcinoma (3 papers, 2016 to 2021). "Similarly, we showed using breast adenocarcinoma-derived cell lines, including MCF7 cells, that CXXC5 is an E2-ER responsive gene and CXXC5 as an unmethylated CpG binder contributes to E2-mediated gene expressions critical for cellular proliferation." (PMID 34341443, 2021). "It is therefore tempting to speculate that E2-ERα, in addition to a direct effect on CXXC5 expression, also modulates the transcriptional output of CXXC5 by regulating gene expressions of and interactions with RARα and WT1 in breast tissue and breast adenocarcinomas." (PMID 27886276, 2016).
Insulin resistance (3 papers, 2022 to 2025). Increased resistance towards insulin, that is, diminished effectiveness of insulin in reducing blood glucose levels. "Furthermore, a study has demonstrated that CXXC5 is associated with genes involved in insulin endocytosis, suggesting a potential role in the regulation of insulin resistance." (PMID 39806388, 2025). "Blocking the CXXC5-Dvl interaction can improve the disease metabolic status of mice, reduce insulin resistance, inhibit adipocyte differentiation, facilitate the regeneration of pancreatic beta-cells, and enhance glucose homeostasis." (PMID 39806388, 2025).
liver fibrosis (3 papers, 2021 to 2025). "For instance, CXXC5 can inhibit the process of liver fibrosis but promote the development of HCC (another study has suggested that CXXC5 can inhibit the growth of HCC)." (PMID 39806388, 2025). "Overall, the recovery of liver fibrosis by blocking the inhibitory function of Cxxc5 on Wnt/β-catenin signaling correlates with activation of the regenerative system in the liver tissue of NASH mice." (PMID 36114279, 2022). "Because CXXC5 deficiency leads to IRF7 up-regulation in mice, which may potentially trigger a pro-fibrogenic response, it would be of great help to examine the phenotype of the CXXC5-null mice in the settings of the liver fibrosis." (PMID 34621736, 2021). "Since the E2-ER axis plays an inhibitory role in HSC activation and liver fibrosis, it is tempting to speculate that CXXC5 repression may be secondary to dampened E2-ER signaling." (PMID 34621736, 2021). "Screening for small-molecule compounds that boost CXXC5 activity could potentially yield novel therapeutic strategies in the intervention of liver fibrosis." (PMID 34621736, 2021). "GO and KEGG analyses showed that several pathways related to liver fibrosis including PI3K-AKT signaling, ECM–receptor interaction, and focal adhesion were altered due to CXXC5 over-expression." (PMID 34621736, 2021). "We first evaluated the relationship between CXXC5 expression and HSC activation in different animal and cell models of liver fibrosis." (PMID 34621736, 2021). "Hepatic fibrosis represents a critical step in the transformation of normal liver cells to HCC, and CXXC5 expression is down-regulated during the activation of hepatic stellate cells, which inhibits the expression of the proto-oncogene MYCL1 by binding to the promoter region of the MYCL1 gene." (PMID 39806388, 2025).